CHRNB1 (cholinergic receptor nicotinic beta 1 subunit)
Description:
After binding acetylcholine, the AChR responds by an extensive change in conformation that affects all subunits and leads to opening of an ion-conducting channel across the plasma membrane.
Synonyms: ACHRB; CHRNB; CMS1D; CMS2A; CMS2C; SCCMS
Tractability: Small molecule: an approved drug acts on it; a high-quality ligand is known; it belongs to a druggable protein family. Antibody: UniProt places it where antibodies can reach, with medium confidence; UniProt predicts a signal peptide or a membrane-spanning region; its Gene Ontology location is reachable by antibodies, with medium confidence. PROTAC: ubiquitination databases record sites on it; a small molecule that binds it is known.
Gene: Protein-coding gene on chromosome 17 (7,445,061 to 7,457,710, forward strand). Ensembl gene ENSG00000170175.
Subcellular location: Postsynaptic cell membrane; Cell membrane
Gene Ontology:
Molecular function: acetylcholine receptor activity; channel activity; protein binding; transmitter-gated monoatomic ion channel activity involved in regulation of postsynaptic membrane potential; acetylcholine binding; acetylcholine-gated monoatomic cation-selective channel activity; ligand-gated monoatomic ion channel activity; neurotransmitter receptor activity; extracellular ligand-gated monoatomic ion channel activity; monoatomic ion channel activity; transmembrane signaling receptor activity
Biological process: behavioral response to nicotine; monoatomic cation transport; muscle cell development; muscle contraction; nervous system process; neuromuscular synaptic transmission; postsynaptic membrane organization; signal transduction; synaptic transmission, cholinergic; acetylcholine receptor signaling pathway; calcium ion transport; membrane depolarization; monoatomic ion transmembrane transport; regulation of membrane potential; skeletal muscle contraction; chemical synaptic transmission; chemical synaptic transmission, postsynaptic; excitatory postsynaptic potential; monoatomic ion transport; regulation of postsynaptic membrane potential
Cellular component: acetylcholine-gated channel complex; neuromuscular junction; synapse; neuron projection; plasma membrane; membrane; postsynaptic membrane; postsynaptic specialization membrane
Genetic constraint (gnomAD): Loss-of-function variants: 47 observed, 57.27 expected, observed/expected ratio (o/e) 0.82, 90% interval 0.65 to 1.05. The upper end of that interval is the gene's LOEUF score, 1.05, which puts it in group 4 of 6, group 1 being the genes least tolerant of losing a copy. Missense variants: 605 observed, 693.39 expected, observed/expected ratio (o/e) 0.87, 90% interval 0.81 to 0.93. Synonymous variants: 259 observed, 276.95 expected, observed/expected ratio (o/e) 0.94, 90% interval 0.84 to 1.04.
Gene-disease validity (ClinGen):
ClinGen rates the evidence that CHRNB1 causes each of these diseases.
congenital myasthenic syndrome 2C (autosomal recessive): Definitive.
congenital myasthenic syndrome 2A (autosomal dominant): Moderate.
Homologues: Orthologues: chimpanzee CHRNB1 (99% identical), macaque CHRNB1 (97% identical), pig CHRNB1 (94% identical), guinea pig CHRNB1 (93% identical), rabbit CHRNB1 (92% identical), dog CHRNB1 (92% identical), mouse Chrnb1 (90% identical), rat Chrnb1 (81% identical), zebrafish chrnb1 (58% identical), zebrafish chrnb1l (53% identical). Paralogues in human: CHRNG (41% identical), CHRNB4 (40% identical), CHRNB2 (39% identical), CHRND (39% identical), CHRNE (38% identical), CHRNA4 (38% identical), CHRNA2 (37% identical), CHRNA3 (34% identical), CHRNA1 (34% identical), CHRNB3 (33% identical), CHRNA6 (33% identical), CHRNA5 (32% identical), and 33 more.
Diseases named in the same sentence as CHRNB1 in open-access papers:
CHRNB1 is named in the same sentence as 21 diseases in open-access papers, as found by Europe PMC text mining. Sharing a sentence is not in itself a finding about the gene and the disease. The quoted sentences say what the papers report.
congenital myasthenic syndrome (5 papers, 2016 to 2024). Congenital myasthenic syndrome (CMS) is a group of genetic disorders of impaired neuromuscular transmission at the motor endplate characterized by fatigable muscle weakness. "CHRNB1 variants are known to cause congenital myasthenic syndrome (CMS2A; OMIM #616313, AD), characterized by abnormal fatigability and transient/permanent weakness of extraocular, facial, bulbar, truncal, respiratory, or limb muscles." (PMID 39202332, 2024).
alcohol dependence (1 paper, 2023). Physical and psychological dependence on alcohol. "All nicotinic receptor genes, except the muscle-type CHRNB1, including eight genomic regions containing 11 neuronal CHRN genes and 3 genomic regions containing 4 muscle-type CHRN genes, have been significantly associated with nicotine dependence and/or alcohol dependence." (PMID 37295945, 2023).
Alzheimer disease (1 paper, 2015). A progressive, neurodegenerative disease characterized by loss of function and death of nerve cells in several areas of the brain leading to loss of cognitive function such as memory and language. "Among the analysed target genes, nicotinic acetylcholine receptors (CHRNB3, CHRNE, CHRNB1, CHRND) were found, which are targets of drugs against Alzheimer's disease." (PMID 26693857, 2015).
myasthenia (1 paper, 2026). "Although most of the patients with mutations in established CMS genes (such as DOK7, MUSK, RAPSYN, CHRNA1, CHRNB1, CHRND, and CHRNE) do not show cognitive symptoms, in some newly identified CMS subtypes, myasthenia is only one element of a more severe and complex clinical spectrum." (PMID 41575592, 2026).
myasthenia gravis (1 paper, 2022). Myasthenia gravis (MG) is a rare, clinically heterogeneous, autoimmune disorder of the neuromuscular junction characterized by fatigable weakness of voluntary muscles. "Other interesting data were the lower gene levels for some of the components of the acetylcholine receptor (CHRNB1, CHRNA1 and CHRNG) that may result in a significant reduction of the amplitude of the transmission signal, as has already been demonstrated for myasthenia gravis patients." (PMID 36359747, 2022).
ptosis (1 paper, 2019). The drooping of the upper eyelid. "The second patient carrying a CHRNB1 mutation was a 3wo male manifesting with ptosis, facial weakness, severe hypotonia, and respiratory insufficiency requiring assisted ventilation." (PMID 30808424, 2019).
tumor (2 papers, 2019 to 2024). "However, we did find the expression of CHRNA1, CHRNA9, and CHRNB1 to be significantly upregulated in the GBM samples in comparison to the non-tumor samples." (PMID 31590360, 2019).
musculoskeletal disorders (1 paper, 2024). "We observed that MYH7, RYR1, FBN1, TNNT1, MYBPC1, COL1A1, and CHRNB1 were related to musculoskeletal disorders." (PMID 38658807, 2024).
CHRNB1 also shares sentences with these, for which no sentence is quoted: arthrogryposis (2 papers); arthrogryposis multiplex congenita (1); brain malformations (1); cancer (1); channelopathies (1); diabetes (1); epilepsy (1); infection (1); Intellectual disability (1); melanoma (1); nicotine dependence (1); Obesity (1); prostate carcinoma (1).